IL1B (interleukin 1 beta)
Diseases named in the same sentence as IL1B in open-access papers (continued):
Sharing a sentence is not in itself a finding about the gene and the disease.
oral squamous cell carcinoma (28 papers, 2014 to 2025). "After exposure of these cells to Interleukin-1 beta (IL-1β, a pleiotropic cancer-inflammation-linked cytokine), an increase in Grx1 was reported, causing a decrease in the levels of ROS and conferring to oral squamous cell carcinoma, invasiveness and migration." (PMID 33932870, 2021). "Melatonin inhibits the development of oral squamous cell carcinoma by interrupting the MIF/NLRP3/IL-1β signaling pathway promoted by macrophages." (PMID 40756978, 2025). "Increased expression of NLRP3 and increased serum IL-1β has been observed in oral squamous-cell carcinoma (OSCC) patients." (PMID 39769450, 2024). "Further, in OSCC, zymosan from candida albicans fungal cell wall has been shown to promote IL-1β production and proliferation of oral squamous-cell carcinoma cells." (PMID 39769450, 2024). "The exposure of oral squamous cell carcinoma cells (CAL27) to Interleukin-1 beta (IL-1β) activity led to an increase in the levels of Grx1 protein." (PMID 38256082, 2024). "Further studies on oral squamous cell carcinoma cells have revealed that IL-1β mediates the formation of the chemokine CXCL1, which leads to a transactivation of EGFR via the G protein-coupled receptor CXCR2." (PMID 34205482, 2021). "Consistent with our findings, in previous studies, CXCL1 expression increased in cocultures of CAF and oral squamous cell carcinoma cells with IL1β, promoting tumor invasion and CAF activity." (PMID 34218518, 2021). "Silencing IL-1β with lentivirus-delivered shRNA significantly inhibited oral squamous cell carcinoma cell growth both in vivo and in vitro." (PMID 26831400, 2016). "For example, interleukin-1 beta (IL-1β), a well-known mediator of chronic inflammation, has been identified as a salivary biomarker for oral squamous cell carcinoma, and increased IL-1β levels have been related to the increased severity of oral malignant transformation in in vivo models." (PMID 37190301, 2023). "Therefore, salivary biomarkers like the pro-inflammatory cytokines IL-1β, IL-2 and TNF might be used as a future diagnostic tool for oral squamous cell carcinoma." (PMID 33153049, 2020). "In addition, elevated salivary IL-1β has been found in oral squamous cell carcinoma patients." (PMID 24465623, 2014). "In oral squamous cell carcinoma, LDOC1 inhibited microbe-induced IL-1β production by regulating the phosphoinositide 3-kinases (PI3K)/protein kinase B (Akt)/phospho-glycogen synthase kinase 3 beta (pGSK-3β) signaling pathway." (PMID 39682774, 2024). "The IL-1β is another inflammatory and cancer-related cytokine which has been recently found to affect EGFR transactivation in oral squamous cell carcinomas." (PMID 33924087, 2021). "The results showed that the presence of oral squamous cell carcinoma influenced the salivary levels of IL-8, IL-6, VEGF, and IL-1β, determining an increased concentration." (PMID 32899735, 2020). "For instance, the NLRP3 inflammasome is activated by 5-fluorouracil (5-FU) in oral squamous cell carcinoma (OSCC) cells, and mediates chemoresistance by inhibiting apoptosis via ROS/IL-1β upregulation." (PMID 32209729, 2020). "Moreover, oral squamous cell carcinoma cell lines, including HSC2, respond to inflammatory cytokines IL1β and TNFα with an increased chemokine expression, including CXCL1, CXCL2, CXCL8, and CCL5." (PMID 39199704, 2024). "Moreover, oral squamous cell carcinoma cell lines, including HSC2, respond to inflammatory cytokines IL1β and TNFα with an increased expression of chemokines such as CXCL1, CXCL2, CXCL8, and CCL5." (PMID 39199704, 2024). "In oral squamous cell carcinoma cells, anthocyanin could reduce the viability, inhibit the migration and invasion abilities and enhance the expression of NLRP3, caspase-1 and IL-1β." (PMID 39616223, 2024). "In oral squamous cell carcinoma, IL1B is overexpressed in tumors as compared with non-tumor matched samples." (PMID 32635472, 2020).
peripheral nerve injury (28 papers, 2008 to 2025). Injury to a peripheral nerve. "IL-1β is one of the first cytokines to be implicated in peripheral nerve injury-induced neuropathic pain." (PMID 37174675, 2023). "After peripheral nerve injury, microglial cells are activated by molecular mediators such as neuregulin-1, chemokine (C–C motif) ligand 2, and fractalkine; activated microglial cells in turn release IL-6, IL-1β, and TNF-α to cause painful symptoms." (PMID 36348269, 2022). "To check whether peripheral nerve injury is associated with IL-1β production at all, we analyzed expression of the whole signaling cascade at the protein level." (PMID 26253422, 2015). "For example, in studies investigating vincristine-induced peripheral nerve injury, vincristine was shown to induce macrophage release of IL-1β through the activation of the NLRP3 inflammasome." (PMID 41573554, 2025). "Pro-inflammatory interleukins, such as IL-1β, IL-6, and IL-17, play a pivotal role in the pathophysiology of peripheral nerve injury." (PMID 41573554, 2025). "Of course, it cannot be ignored that interleukins exhibit a time-dependent bidirectional effect in the repair of peripheral nerve injury, such as factors like IL-1β, IL-6, and IL-17." (PMID 41573554, 2025). "In SC, proinflammatory cytokines IL-1β and IL-6 have been generally reported to be increased after peripheral nerve injury." (PMID 36830952, 2023). "Previous reports suggest that increased production of pronociceptive interleukins (e.g., IL-1β, IL-18, and IL-6) by immune and glial cells after peripheral nerve injury contributes to the development and maintenance of neuropathic pain." (PMID 34681732, 2021). "Activation of miR-195 by peripheral nerve injury aggravates neuropathic pain via autophagy and this also leads to increases of IL-1β, and TNF-α." (PMID 32296644, 2020). "The pro-inflammatory cytokines, especially TNF-α and IL-1β, induced by peripheral nerve injury, are essential triggers for the activation of JNK in spinal astrocytes underlying the development of neuropathic pain." (PMID 25889689, 2015). "Together, our observations suggest that Nlrp6 contributes to recovery from peripheral nerve injury by dampening inflammatory responses independently of IL-1β and inflammasomes." (PMID 26253422, 2015). "Inhibiting proinflammatory factor IL-1β contributed to the synergistic effects of tramadol and propentofylline coadministration on rat peripheral nerve injury-induced neuropathic pain." (PMID 24009718, 2013). "Finally, we also address the importance of sNAMs for the production of pro-inflammatory cytokines, especially TNF and IL-1b, which have been described as upregulated in the sensory ganglia after peripheral nerve injury." (PMID 37254842, 2023). "In addition, the activation of microglial cells following peripheral nerve injury facilitates persistent pain via p38 and IL-1β mediation." (PMID 37239279, 2023). "The goal of the current experiment was to assess whether spinal IL-1β is necessary for a 10-day allodynia in PAE rats induced by minor peripheral nerve injury." (PMID 30961664, 2019). "More importantly, increased extracellular glutamate release following nerve injury stimulates glutamate receptors, which in turn activate microglia to induce the release of cytokines such as IL-1β in the hippocampus, which could be relevant to peripheral nerve injury." (PMID 37239279, 2023). "Additionally, peripheral nerve injury also leads to the activation of peripheral (Schwann cells) and central (microglia and astrocyte) glial cells and begins to secrete proinflammatory cytokines, including TNFα, IL-1β, and PGE2." (PMID 35685245, 2022). "In case of peripheral nerve injury, the damaged neurons send excitatory signals to the spinal microglia via chemical substances, such as ATP and chemokines; these, in turn, cause microglial proliferation and upregulation of inflammatory cytokines, such as TNF-α, IL-1β, and IL-6, resulting in NP." (PMID 32636748, 2020).
peripheral nerve injury (continued). "However, no significant changes in the expression of macrophage/glial cell activation markers and their derived pro-nociceptive cytokines (TNF and IL-1β) were detected after peripheral nerve injury in the DRGs and spinal cord from IL-27 null mice compared to WT mice." (PMID 32047492, 2019). "SC, the most abundant peripheral glial cells, respond to peripheral nerve injury by the way of changing phenotype and releasing of inflammatory mediators (TNF-α, IL-6, and IL-1β), which leads to the exacerbation of NP." (PMID 34630095, 2021). "During peripheral nerve injury, activated glial cells release TNF-α and IL1-β, which affect the neurons and amplify the pain response." (PMID 28793053, 2017). "Along with this immune cell infiltration, various proinflammatory cytokines and chemokines, including TNF-α, IL-1β, and MCP-1, are expressed in the DRG of injured nerves after peripheral nerve injury." (PMID 21951975, 2011). "Thus, the present study was designed to determine whether IL-1β modulates astrocyte P450c17 expression and astrocyte activation in the spinal cord and to determine whether this modulation alters the development of neuropathic pain following peripheral nerve injury." (PMID 31281242, 2019). "It is also known that peripheral nerve injury induces the expression of proinflammatory cytokines, such as TNF-α and IL-1β, in the DRG and that these cytokines may play a role in the development of pain hypersensitivity." (PMID 21951975, 2011). "Contrary to these results, it was shown that although spinal glial-derived IL-1β is fundamental for the development of neuropathic pain after peripheral nerve injury, caspase-1 is not involved in this process." (PMID 20920345, 2010). "Our results indicate that the PAF/PAFR system has an important role in production of TNFα and IL-1β in the DRG and tactile allodynia following peripheral nerve injury and suggest that blocking PAFRs may be a viable therapeutic strategy for treating neuropathic pain." (PMID 20454616, 2010). "Therefore, while we could not detect a role for IL-1β for functional recovery of the nerve, we could see that overactivation of the inflammatory response aggravates peripheral nerve injury." (PMID 26253422, 2015).
rheumatic diseases (28 papers, 2010 to 2025). "MAS is a form of HLH seen in rheumatic disorders, caused by dysregulated immune activation and excessive cytokine production (IL-1β, TNF, IFN-γ), leading to hyperinflammation and tissue damage." (PMID 40385895, 2025). "In a recent phase III clinical trial, canakinumab, a monoclonal antibody inhibitor of interleukin-1 beta (IL1b) which has a license for rheumatological disorders, was shown to lower the risk of cardiovascular diseases." (PMID 35292824, 2022). "Inflammasome-derived IL-18/IL-1β were suggested to play important roles in MAS-associated rheumatic diseases." (PMID 34239943, 2021). "The role of IL-1β in rheumatic diseases is well established, primarily because of the infiltration of myeloid cells into inflamed joints, where they produce IL-1β." (PMID 41087719, 2025). "Proinflammatory cytokines such as TNFα (tumor necrosis factor alpha), IL-6 (interleukin 6) and IL-1β (interleukin 1 beta), which circulate in the systemic blood flow in rheumatic diseases, influence the brain structures." (PMID 39845811, 2024). "IL‐1β is known to play an important role in rheumatic diseases, but the upstream mechanisms leading to production of this interleukin are still incompletely understood." (PMID 37694693, 2023). "Inhibition on TNF-α and IL-1β has been demonstrated to reduce neutrophil infiltration and pain in rheumatic disease." (PMID 34586567, 2022). "A recent study showed that pro-inflammatory macrophages (M1) exhibit effector potential through activation of NLRP3 inflammasome leading to the production of IL-1β and IL-18, an important pathway in the pathogenesis of rheumatic diseases." (PMID 33537348, 2020). "Overall, the strong inflammatory effect of RBP4 and its synergic activity with IL1β might explain the contribution of certain metabolic diseases to the development of rheumatic diseases." (PMID 38275649, 2024). "In this review, we will examine the respective roles of IL-1β and type I IFNs in autoinflammatory/rheumatic diseases and analyze their potential connections in the pathophysiology of some of these diseases, which could reveal novel therapeutic opportunities." (PMID 34066649, 2021). "IL-1β seems to play an important role in the pathogenesis of various rheumatic diseases." (PMID 35154066, 2021). "Studies showing that injection of some of the key cytokines produced in rheumatic diseases into HC, such as IL-1β or IL-6, produces fatigue and that biologics targeting IL-6 or TNF-α ameliorate fatigue suggest a role for these molecules in the development of fatigue." (PMID 31685018, 2019). "Moreover, targeting TNF-α, IL-1β, or IL-33 in rheumatic diseases reduce neutrophil recruitment and pain." (PMID 30333752, 2018). "Furthermore, we analysed the role of IL-1β in bone resorption during rheumatic diseases and, when available, we reported the efficacy of anti-IL-1β therapy in this field." (PMID 25954061, 2015). "Furthermore, we analyzed the role of IL-1β in bone resorption during rheumatic diseases and, when available, we reported the efficacy of anti-IL-1β in this field." (PMID 25954061, 2015). "Regarding rheumatic diseases, a collagen-induced arthritis mouse model exhibited notable improvements in MMP-3 (Matrix Metalloproteinase-3), IL-17 (Interleukin-17), TNF-α, IL-1β (Interleukin-1 beta), IFN-γ, and IL-6 levels when mice were fed with an oleocanthal-rich diet." (PMID 38136231, 2023). "For example, IL-37, a member of the IL-1 family which is stimulated by SARS-CoV-2, has been shown to suppress IL-1β, IL-6, TNFα and CCL2 in rheumatic diseases by acting on mTOR and enhancing the AMPK activity, to maintain mitochondrial membrane potential and limit the toxic effects of ROS." (PMID 36389723, 2022).
rheumatic diseases (continued). "The effect of rheumatism in the JWFSN-middle and JWFSN-high dose groups is particularly obvious, suggesting that the therapeutic effect of JWFSN on CIA rats may be through direct or indirect reduction of TNF-α, IFN-γ, and IL-1β expression and improve IL-4 and IL-10." (PMID 31929822, 2019).
sarcoidosis (28 papers, 2012 to 2025). Sarcoidosis is a multisystemic disorder of unknown cause characterized by the formation of immune granulomas in involved organs. "In the context of sarcoidosis, granulomatous inflammation is characterized by the dominant expression of the critical cytokines, GM-CSF, IL-1β and T helper 1 (Th1) cytokines, including IFN-γ and TNF-α." (PMID 41476976, 2025). "The levels of IL-1β were slightly lower in sarcoidosis patients than in HP (p = 0.04) and amiodarone lung (p = 0.03) patients, and the levels of IL-2 were higher in sarcoidosis patients than in amiodarone lung (p = 0.006) patients." (PMID 40725075, 2025). "Sarcoidosis patients had decreased levels of IL-1β, IL-5, IL-8, IL-12p70, TNF-α, angiogenin, C3a, C4a, RANTES, and MCP-1 and increased levels of IL-2, IL-4, IL-6, IL-13, IFN-γ, and VEGF." (PMID 40725075, 2025). "We identified nine biomarkers (IL-1β, IL-6, IL-8, IL-13, VEGF, angiogenin, C4a, RANTES, and MCP-1) that significantly differ in the BAL of patients with HP and sarcoidosis and showed that RANTES and IL-6 are associated with fibrotic outcome." (PMID 40725075, 2025). "It is reported that downregulated mRNA levels of miR-223, a direct downregulator of the NLRP3 inflammasome, induce the increased expression of IL-1β in AMs from sarcoidosis patients than in healthy volunteers." (PMID 35819638, 2022). "Broncho-alveolar lavage fluid of sarcoidosis patients showed increased levels of exosomes inducing various pro-inflammatory cytokines, such as IL-1β, IL-6, and TNF (Tumor Necrosis Factor) alpha." (PMID 34440765, 2021). "Increased expression of IL-1β by BAL MNPs indicates an upregulation of the inflammatory NLRP3 pathway as previously shown to be activated in sarcoidosis." (PMID 33446605, 2021). "The regulatory effect of HIF-1α on IL-1β expression has been studied in the context of sarcoidosis, infections, and cancer." (PMID 34497517, 2021). "In support of a direct effect on monocytes, the same group of researchers recently reported that EVs from BAL samples of sarcoidosis patients induced dose-dependent elevation of IL1-β in monocytes, confirmed also in PBMCs and enriched monocytes." (PMID 34947932, 2021). "HIF-1α expression has recently been found to be upregulated in sarcoidosis CD14 monocytes and associated with regulation of IL-1β and IL-17 production; here, we confirmed upregulation of HIF1A in these cells." (PMID 33363531, 2020). "IL1-β, TNF and IL-6 are all fundamentally associated with sarcoidosis, and CCL2 is a potent chemotactic agent for monocytes and T cells, and is strongly increased in BAL fluid of sarcoidosis patients." (PMID 32948789, 2020). "CHQ significantly decreased anti-CD3 induced IL-1β and IL-17 production in sarcoidosis PBMCs (p < 0.05)." (PMID 30946009, 2019). "Sarcoidosis AMs exhibited a variable amount of Glut1 and pro-IL-1β (18/18 patients) but only 1 out of 10 healthy controls showed expression." (PMID 30946009, 2019). "Down regulation of HIF-1α expression via short interfering RNA (siRNA) decreased IL-1β in sarcoidosis AMs, while decreased HIF-1α expression in PBMCs decreased IL-1β and IL-17 in response to anti-CD3 challenge." (PMID 30946009, 2019). "The results showed that unstimulated and LPS-stimulated cultured sarcoidosis AMs and monocytes secrete higher IL-1β as compared to healthy controls." (PMID 30946009, 2019). "First, we assessed the effect of anti-CD3 activation on the production of IL-1β and IL-17 in healthy controls and sarcoidosis PBMCs." (PMID 30946009, 2019). "Since the sarcoidosis AMs produced significantly high levels of IL-1β, we assessed the conditioned media for the secreted IL-1Ra." (PMID 30946009, 2019). "The contribution of IL1β was also assessed in 22 patients with active sarcoidosis compared to 22 controls." (PMID 28109186, 2017). "Levels of IL-1β and IL-10 were significantly elevated in both diseases compared to healthy BALs, whereas levels of IL-2 were significantly increased in sarcoidosis only." (PMID 22815689, 2012).